STMN1 (stathmin 1)
Diseases named in the same sentence as STMN1 in open-access papers (continued):
Sharing a sentence is not in itself a finding about the gene and the disease.
tumor (continued). "HELLS, RRM2, and STMN1 expression were positively associated with tumor purity." (PMID 36304446, 2022). "Additionally, G6PD, HELLS, RRM2, and STMN1 were positively associated with higher tumor stage, grade, age, sex, and ethnicity, suggesting an influential contribution to the pathogenesis of HCC." (PMID 36304446, 2022). "STMN1 is an oncogene that is highly upregulated in many tumors and associated with tumor growth." (PMID 34489401, 2021). "Loss of STMN1 sensitizes HCC tumor cells to microtubule-targeting agents, including paclitaxel." (PMID 34834551, 2021). "The EBV-miR-BART6-3p/LOC553103/STMN1 axis inhibits EBV-associated tumour cell proliferation." (PMID 34034760, 2021). "Likewise, in ESCC, stathmin-1 was linked to tumour invasiveness and is proposed as a predictor of poor prognosis." (PMID 34205183, 2021). "The growing expression of miR-770 (acting as a tumor suppressor, direct targets at STMN1) from TNBC cells to tumor-associated macrophages (TAMs) through exosome delivery modulated more differentiation to M1 phenotype instead of M2 phenotype and inhibited drug-resistance." (PMID 31395836, 2019). "Further experiments proved miR-770 could antagonize the chemo-resistance and metastasis via targeting of STMN1, and modify the tumor microenvironment via transportation to tumor-associated macrophage." (PMID 29323124, 2018). "STMN1 encodes a regulatory protein that participates in assembly and disassembly of the mitotic spindle, facilitating the achievement of mitosis process and uncontrolled proliferation of malignant tumor cells." (PMID 28056823, 2017). "Using the multivariate Cox proportional hazards model, we calculated a new risk score for individuals to include these factors, where risk score = 0.173*STMN1–0.608*Ser16+0.743*Ser25+0.685* Ser38–0.342*Ser63+0.459*histological grade+0.448*tumor size+0.946*lymphatic metastasis." (PMID 26087399, 2015). "In the tumor lesion, a malignant STMN1+HMGN2+GPC3+ cell subtype enriched in MVI+ HCC was identified, which exhibited enhanced proliferative activity and was associated with poor prognosis." (PMID 42139279, 2026). "circFOXK2 was highly upregulated in NSCLC compared to control non‐tumor tissues, and the silencing of STMN1 contributed to the downregulation of circFOXK2." (PMID 40013670, 2025). "UCA1, a lncRNA significantly upregulated in chemotherapy-resistant tumor tissues and cell lines, inhibits miR-513a-5p, subsequently upregulating Stathmin 1 (STMN1) expression." (PMID 40191723, 2025). "This temperature elevation not only facilitated the further release of PTX and STMN1-siRNA but also reached the optimal temperature required for effective tumor hyperthermia." (PMID 41361792, 2025). "STMN1 can enhance the radioresistance of tumor cells by increasing autophagy, and it can mediate drug resistance in tumors through the AKT and EGFR‐related pathways." (PMID 40013670, 2025). "STMN1, a microtubule-regulating protein highly expressed in tumors, promotes tumor cell proliferation, invasion, and MDR; silencing UCA1 reduces STMN1 expression." (PMID 40191723, 2025). "The HAI-1, STMN-1 and TN-C proteins, different in terms of their function, whose activity has been observed in various types of neoplasms, inspired us to study them in BC." (PMID 40507426, 2025). "Through co‐immunoprecipitation and mass spectrometry experiments, we found that circFOXK2 interacts with PABPC1, and the circFOXK2/PABPC1 complex maintains the stability of STMN1 mRNA, promoting the process of tumor epithelial–mesenchymal transition (EMT)." (PMID 40013670, 2025). "In NSCLC, HMGA1 interacts with STMN1 to regulate its phosphorylation levels at Ser16 and Ser38, thereby reducing microtubule stability and promoting tumour metastasis." (PMID 39828988, 2025). "STMN1 is highly expressed in many tumor cell types and promotes cell proliferation, migration, and invasion." (PMID 40319242, 2025).
tumor (continued). "Specially, SPP1+ TAMs and STMN1+ TAMs were enriched in tumor core region, and SPP1+ TAMs showed the highest RO/E value of 4.74." (PMID 40230843, 2025). "A key finding of this study is the potential direct transcriptional regulation of STMN1 by E2F1 and the correlation between STMN1 expression and RB1 loss, a critical tumor suppressor in PCa." (PMID 39776361, 2025). "A key finding of this study is the correlation between STMN1 expression and the loss of RB1, a critical tumor suppressor that regulates the cell cycle by binding to E2Fs and blocking their transcriptional activation." (PMID 39711570, 2024). "Its encoded protein, stathmin 1, was found to be upregulated in HCC and associated with cancer cell proliferation, polyploidy and tumor-cell invasion." (PMID 39323867, 2024). "This led the researchers to believe that tumor progression was impacted by site-specific phosphorylation of STMN1 at ser25 and ser38 and subsequent GRP78 binding." (PMID 39057719, 2024). "In this study, we evaluated STMN1 expression across various PCa tumor grades and different prostatic cell types." (PMID 39711570, 2024). "Collectively, STMN1 expression was detected in NE cells of both murine normal prostate tissues and human benign prostate tissues." (PMID 39711570, 2024). "The neuronal marker STMN1, or Oncoprotein18, is overexpressed in a wide variety of various tumor cells and nerve cancers." (PMID 37760452, 2023). "A study observed that IL-32 was involved in MRS2, and interacted with STMN1+ mononuclear/macrophage cells, thereby inhibiting tumor development." (PMID 36937389, 2023). "Knockdown of STMN1 significantly reduces tumor growth and metastasis and induces apoptosis in preclinical experiments." (PMID 37305581, 2023). "In NB tumor sections, STMN1 was expressed in the cytoplasm of neuroblasts and a neuropil-like background in a relatively uniform pattern." (PMID 37760452, 2023). "A first study on STMN1 expression in MPM detected increased protein levels in 7 of 8 MPM tumor samples, and knockdown of STMN1 in MPM cells led to inhibition of cell proliferation and motility." (PMID 37305581, 2023). "High STMN1 expression in tumor tissues correlates with tumor aggressiveness, poor prognosis, and therapeutic resistance in several cancers." (PMID 37760452, 2023). "Knocking down STMN1 in cancer cells leads to cell cycle stagnation in the G2/M phase, thereby increasing tumor sensitivity to paclitaxel and vincristine." (PMID 36127700, 2022). "From the cell ratio, it can be seen that Monocytes_IGHG3 is only present in cancer tissues, Monocytes_APOE is also abundant in tumor tissues, and Monocytes_STMN1 is more distributed in healthy tissues." (PMID 36569220, 2022). "MPM tumor tissues as well as MPM cell lines express low levels of miR-223–3p, which behaves as a tumor suppressor by inhibiting Stathmin (STMN1)." (PMID 37323368, 2022). "To consolidate the correlation between STMN1 and tumor metastasis, we broadly analyzed the clinical cases of HCC through a screening on a large-scale of HCC specimens." (PMID 35210426, 2022). "Next, immunostaining assay indicated that STMN1 in tumor tissues was significantly higher than that in the matched para-tumor tissues while its expression levels at the site of tumor periphery was higher than that in tumor center." (PMID 35210426, 2022). "The results revealed that the mean methylation levels of G6PD, HELLS, RRM2, and STMN1 were significantly lower in HCC tissues than in peri-tumor tissues." (PMID 36304446, 2022). "The result showed that STMN1 was the most stably up-regulated gene in HCC tumor tissues among the total of 75 genes (p = 1.35e-7)." (PMID 35210426, 2022).
tumor (continued). "STMN1 was found to be linked with B cells, CD8+ T cells, CD4+ T cells, macrophages, neutrophils, and monocytes in tumor immune infiltration." (PMID 36127700, 2022). "Recent publications indicated that STMN1 promoted tumor invasion and metastasis through regulating the progress of EMT and the microtubule polymerization." (PMID 35210426, 2022). "The results revealed that when the prognostic indicator was OS, high grade residual tumor, metastasis, positive margin status, high expression of HELLS and STMN1, low expression of EPAS1, CXCL2, NQO1, IL6 were associated with poor prognosis." (PMID 34982796, 2022). "STMN1 expression is elevated in metastatic PCa, and knockdown of STMN1 resulted in reduced proliferation and invasion of PCa cells in vitro as well as tumor growth and metastasis in vivo." (PMID 36139695, 2022). "Our analyses identified a significant downregulation of STMN1 in all tumour lines relative to the average control, suggesting reduced cell proliferation and tumour cell migration." (PMID 36142793, 2022). "It was showed that overexpression of STMN1 in FoxM1-knockdown cells partially rescues the tumor growth in nude mice." (PMID 33526768, 2021). "Three epithelial cell clusters (Epi_KRT19, Epi_STMN1, Epi_FABP1) were almost only presented in tumor tissues." (PMID 35087839, 2021). "In conclusion, our results first demonstrated that circβ-catenin was upregulated in GBC and regulated tumor growth and tumor Warburg effect through miR-223 upregulating its targeting STMN1." (PMID 34489401, 2021). "HN1, interacting with STMN1, reduces α-tubulin acetylation and promotes tumor progression through EMT." (PMID 34568022, 2021). "All data suggested that STMN1 plays a critical role in promoting tumor cell proliferation and sustaining cell cycle/mitosis in multiple types of cancer cells in vitro." (PMID 33526768, 2021). "The tumor suppressive roles of STMN1 were demonstrated by observing the reduced invasiveness of STMN1-restored CRCSCs and decreased motility of STMN1-overexpressed HT29 cells, a CRC cell line exhibits higher stem-like properties." (PMID 33921319, 2021). "A nude mouse xenograft model was used to examine the functions of circST6GALNAC6/STMN1 in tumour metastasis in vivo." (PMID 33568625, 2021). "Previous studies have shown that STMN1 is frequently overexpressed in HCC, which is associated with tumor progression, early recurrence, and poor prognosis." (PMID 33922244, 2021). "When compared with the adjacent normal tissues, HCC tumor tissues indeed displayed higher STMN1 mRNA expression (the left part)." (PMID 33922244, 2021). "In order to elucidate the role of the signature genes’ biological functions, the association of STMN1, RAP1A, FLT3, HSPA8, ANGPT2, and PGF was positively associated with tumor purity in HCC." (PMID 34178637, 2021). "But there is a significant positive correlation of FoxM1 and STMN1 in most of the tested tumor cell lines." (PMID 33526768, 2021). "Increased STMN1 expression has been observed in numerous human tumors including HCC, which is associated with aggressive tumor phenotypes and poor prognosis." (PMID 33922244, 2021). "VEGFR2 and TUBB3 are the drug action targets of Ramucirumab and TXT, respectively, and STMN1 has been suggested to be a marker of tumor resistance to taxanes." (PMID 32993587, 2020). "These miRNAs targeted the expression of stathmin-1 and insulin-like growth factor-1 receptor in the tumor cells, functionally inhibiting their proliferation level." (PMID 33066331, 2020). "Since p27 functions in dual roles, as an oncoprotein via its interaction with STMN1, and as a tumor suppressor via its regulation of cell cycle control, we determined the effect of drug treatments with gemcitabine and AZD1775 on p27 status." (PMID 30992462, 2019). "The cBio Portal generated a network showing that ENO1, PTGES3, NPM1 and STMN1 are connected in this tumor." (PMID 29545914, 2018).
tumor (continued). "In a word, we proved that the tumor suppression effect of miR-770 was mediated by targeting of STMN1, which has been demonstrated as a tumor promoter in kinds of cancers." (PMID 29323124, 2018). "Taken together, these results suggested that STMN1 was required for tumor growth in a mouse model of GBC." (PMID 27349455, 2016). "Stathmin (STMN1), a recognized oncoprotein upregulated in various solid tumors, promotes microtubule disassembly and modulates tumor growth and migration activity." (PMID 27934948, 2016). "One previous study confirmed that STMN1 is a target of miR-223 and that downregulation of miR-223 contributes to chemoresistance in various cultured tumor cells." (PMID 27577078, 2016). "Susceptibility to docetaxel was evaluated in miR-223/STMN1-modulated GBC cells and xenograft tumor models." (PMID 27577078, 2016). "Immunohistochemical findings revealed that expression of THRs was markedly decreased in tumor specimens, whereas STMN1 levels were enhanced." (PMID 27934948, 2016). "STMN1 expression in the tumor was examined by immunohistochemistry and showed weaker staining in miR-223-expressing tumors than in scramble control tumors." (PMID 27577078, 2016). "MiR-193b has been shown to regulate the expression of stathmin 1 and consequently affected tumour growth and metastasis in pancreatic cells." (PMID 26878873, 2016). "Eight separate prognostic factors emerged: STMN1, Ser16, Ser25, Ser38, Ser63, histological grade, tumor size and lymphatic metastasis." (PMID 26087399, 2015). "The PIWIL1/STMN1/tubulin complex suppresses MT polymerization and thus promotes tumor cell migration and proliferation." (PMID 26317901, 2015). "Given the critical role of PABPC1 in mRNA stability, we aimed to investigate whether circFOXK2 promotes mRNA stability by interacting with PABPC1, thereby affecting STMN1 expression and driving tumor progression." (PMID 40013670, 2025). "We demonstrated STMN1 expression in patient tumor specimens via immunohistochemistry (IHC)." (PMID 40225568, 2025). "In addition, immunofluorescence staining of tumor tissue sections demonstrated that STMN1 interference led to a significant reduction in green fluorescence-labeled STMN1." (PMID 41361792, 2025). "Collectively, these observations imply that different tumor cell types express varying levels of STMN1, and analysis of STMN1 expression and function at the cellular level would be more reflective of the role STMN1 plays in promoting tumor growth and metastasis." (PMID 40723207, 2025). "Consequently, the definitive causal role of STMN1/PRDX1 in regulating LDHA/GPX4 and driving tumor progression in a physiological context remains to be established." (PMID 41403955, 2025). "In CRC patients, CIC structures are associated with poor tumor differentiation, negative STMN1 expression, and poor prognosis." (PMID 40225568, 2025). "However, the staining intensity of the signature proteins—PML, G6PD, SLC7A11, and STMN1—in the tumor tissues was notably stronger than that in the paired adjacent tissues." (PMID 38317842, 2024). "Here, we found that STMN1 mRNA was also highly expressed in NSCLC tumor tissues." (PMID 38385074, 2024). "Moreover, the elevated expression of STMN1 observed in proliferating PCa cells and its positive correlation with tumor grades and poor clinical outcomes underscore its potential as a prognostic marker in PCa." (PMID 39711570, 2024). "MiR-770 acts as a potential tumor suppressor by targeting STMN1 to downregulate it." (PMID 38691224, 2024). "Moreover, elevated STMN1 expression in both the tumor and senescent groups indicates worse outcomes in the Kaplan–Meier survival curves compared to the low expression group, suggesting a poor prognosis." (PMID 39457014, 2024). "However, there is also a different view on the role of STMN1 in tumor metastasis; for example, a study showed that STMN1 was negatively related to EMT20." (PMID 38385074, 2024).
tumor (continued). "This regulation of STMN1 in turn affects apoptosis, epithelial-mesenchymal transition, metastasis, and chemoresistance to doxorubicin in triple-negative breast cancer, thereby altering the tumor microenvironment." (PMID 38691224, 2024). "Many downregulated genes in tumour‐infiltrating peripheral CD8+ T cells are associated with classical IFN responses (IFI6, IFI27, MX1, STAT1, EPSTI1 PARP9, ISG15), cell proliferation (STMN1, CENPF, HELLS, NUSAP1, and DNPH1), and T cell costimulation (CD28, TMIGD2, TNFRSF4, CD27, and TNFRSF18)." (PMID 39350478, 2024). "STMN1 contributes most likely to tumor spread and dissemination." (PMID 38275417, 2024). "Considering that HMGA1 was highly associated with tumor metastasis and that HMGA1 interacted with STMN1, we speculated that HMGA1 may be involved in the biological process by which STMN1 promotes NSCLC metastasis." (PMID 38385074, 2024). "The other group comprises macrophage subgroups, including Mφ-STMN1, Mφ-ISG15, tissue-resident macrophages (RTM-LMNA, RTM-MARCO), tumor-associated macrophages (TAM-MMP12, TAM-SPP1, TAM-CXCL10, TAM-HLA-DQA1), and myeloid-derived suppressor cell-like cells (MDSClike-IL10)." (PMID 39308672, 2024). "We hypothesize that cell cycle dysregulation based on microtubule dynamics dysfunction is the main mechanism of the anti-tumor effect of STMN1 silencing." (PMID 37760452, 2023). "MAX, DCAF7, and STMN1 were identified as novel targets of miR-193a, which may contribute to its anti-tumor effect." (PMID 37443682, 2023). "We hypothesize that microtubule dynamics dysfunction is the main mechanism of the anti-tumor effect of STMN1 silencing." (PMID 37760452, 2023). "In addition, cPKM can upregulate the expression of STMN1, a gene closely related to tumor occurrence, progression, and paclitaxel resistance, thus enhancing the proliferation, metastasis, and paclitaxel resistance of ICC cells." (PMID 37789644, 2023). "Therefore, it was confirmed that STMN1 is extensively involved in the regulation of various immune molecules in HCC to influence immune invasion in the tumor microenvironment." (PMID 36127700, 2022). "Simultaneously, we discovered that STMN1 expression was associated with immune modulators and chemokines, indicating that STMN1 is engaged in regulating a variety of immune components in HCC to influence immunological invasion of the tumor microenvironment." (PMID 36127700, 2022). "In the literature, there are no studies investigating autophagy, apoptosis, and invasion mechanisms in the pharmacological inhibition of STMN1, which will increase the effect of microtubule inhibitors used in the treatment of PCa and at the same time, reduce tumor proliferation." (PMID 37529254, 2022). "In addition, the expression levels of STMN1 in MVI tissues were significantly higher in regular tumor tissues." (PMID 35210426, 2022). "In anaplastic thyroid carcinoma, HN1 could promote tumor growth and metastasis by interacting with STMN1." (PMID 35186166, 2022). "Furthermore, increased STMN1 expression was linked to HCC patients’ age, gender, AFP level, tumor status, clinical stage, and histological grade." (PMID 36127700, 2022). "Moreover, pathological analysis of tumor tissue sections showed a much higher frequency of the occurrence of abnormal cell division in STMN1-knockdown groups." (PMID 33526768, 2021). "Stathmin-1 is a microtubule-destabilizing cytosolic phosphoprotein, which is post-transcriptionally regulated by miR-34a, miR-223, and miR-193b, and plays a central role in tumour cell proliferation and migration." (PMID 34205183, 2021). "First, our findings mainly rely on CRC cell line-derived cell models, primary cells or CSCs isolated from different tumor types may help to delineate dual roles of STMN1 under diverse context of cells or tissues." (PMID 33921319, 2021).